CCR2 (C-C motif chemokine receptor 2)
Diseases named in the same sentence as CCR2 in open-access papers (continued):
Sharing a sentence is not in itself a finding about the gene and the disease.
glioma (continued). "TAMs could be recruited to tumor site by an interaction between CCL2 (constitutively produced by glioma cells) and its receptor CCR2 (expressed on TAMs), what confirms the importance of chemokines as the key players in GBM progression." (PMID 32456359, 2020). "Glioma-derived CCL2 acts on microglia with CCR2 and then produces IL-6 to stimulate the glioma." (PMID 33511267, 2020). "We speculate that CCR2-dependent myeloid cells are crucial to controlling glioma growth while the remaining CCR2-independent TAMs are unable to arrest or decelerate tumor expansion." (PMID 32668709, 2020). "Thus, Imaging-Community-AMARETTO (Appendix Fig A1) identified THBS1 and MAP2 as novel master drivers across the three STAT3, AHR, CCR2, and OLIG2 communities that provide new insights into how these distinct key mechanisms are linked in glioma." (PMID 32383980, 2020). "Interestingly, we found reduced IFNγ expression and increased PDL1 signal in gliomas of Ccr2-/- mice that indicated a rather immunosuppressive milieu in these tumors." (PMID 32668709, 2020). "Importantly, CCL2 then recruits regulatory T cells (Tregs) and myeloid-derived suppressor cells (MDSCs) through CCR4 and CCR2 as significant contributors to the potently immunosuppressive glioma microenvironment." (PMID 32296458, 2020). "Additionally, we investigated surgically resected human brain tissues at our institution and observed CCR2 positive staining both in epilepsy (EP) (3/3) as well as GBM tissue samples (6/6) revealing variable expression levels in glioma specimens." (PMID 32668709, 2020). "Moreover, glioma monocytes and macrophages can be identified based on the expression of Ly6c, Ccr2, Cx3cr1, Cd64, Mertk, Cd45, F4/80, Ccr7 and transcription factor Nr4a113." (PMID 32555306, 2020). "FACS measurements showed increased VCAM1-positive TAMs and CCR2+ TAM precursor cells in Sr-a1−/− glioma compared with Sr-a1+/+ glioma, confirming that SR-A1 deletion could increase TAM infiltration." (PMID 27367025, 2016). "Overexpression of CCL2 in the U87 glioma cell line was recently shown to enhance its invasiveness in a three-dimensional collagen matrix when these cells were cocultured with microglia (which express the CCL2 receptor CCR2)." (PMID 23864876, 2013). "Human glial tumors are known to express CCR2, though the biological significance of this observation is unknown." (PMID 21943176, 2011). "Targeting myeloid cells by disrupting the CCL2/CCR2 axis, which regulates monocyte and macrophage recruitment to the tumor microenvironment, can limit the infiltration of pro-tumorigenic myeloid cells and enhance anti-tumor immune responses in experimental gliomas." (PMID 40281508, 2025). "Considering the holistic concept of the glioma microenvironment, other microenvironmental components such as microglia may also be part of the extra source of these effector molecules like IL-6 and CCR2." (PMID 40243478, 2025). "We speculate that these are mainly glioma cells that are known to express CCR2." (PMID 32668709, 2020). "Interestingly, while the CCL2/CCR2 signaling axis seems to be the main attractant for monocytes at the later stages of glioma growth, we show that Sdf1b/Cxcr4b signaling is responsible for macrophage infiltration during the initial stages of oncogene activation in the brain." (PMID 29465400, 2018). "CCL2, a CC chemokine that stimulates CCR2, its corresponding receptor expressed on T cells, NK cells and γδ T cells, is reported to be expressed by various types of cancer cells including those of glioma, melanoma, and cancers of the breast, prostate, colon and lung." (PMID 23441216, 2013). "By targeting pathways that recruit and sustain macrophages, we found that CCR2-KO mice had significantly reduced MDSC and macrophage infiltration in the glioma TME 18,70-74." (PMID 40661379, 2025). "Human glioma cells induce microglia to secrete and release IL-6 through CCL2/CCR2 axis, thus promoting glioma invasion." (PMID 38229178, 2024).
glioma (continued). "In gliomas, CCL2's production is vital for recruiting immunosuppressive CCR4+ Tregs and CCR2+ Ly‐6C+ monocytic myeloid‐derived suppressor cells." (PMID 39706820, 2024). "This study evaluated the mechanism of CCR2+/CX3CR1+ M-MDSC differentiation and T cell suppressive function in murine glioma models." (PMID 39272914, 2024). "In the tumor microenvironment of human gliomas, CCL2 has been shown to recruit both CCR4+ Treg and CCR2+ Ly6C+ monocytic myeloid-derived suppressive cells." (PMID 38213329, 2023). "Specifically, MDM markers, including Ly6C and CCR2, were downregulated during MDM activation or differentiation in the glioma microenvironment." (PMID 37365324, 2023). "Observational studies have found that angiogenic factors (CCR2, VEGF-A, etc.)are overexpressed in glioma cells with high levels of VASN." (PMID 36910644, 2023). "Chemokines and paired receptors, including CCL2 and CCR2, were upregulated in TANK-expressing gliomas." (PMID 37215097, 2023). "Here, the selective CCR2 antagonist RS504393 that inhibits the infiltration of immunosuppressive MDSC into the TME in a bladder cancer mouse model or CCL2 specific antibodies such as C1142 inhibiting tumor progression in a glioma model might be interesting novel agents." (PMID 37849753, 2023). "These immune cells had the highest density in gliomas and possessed immunosuppressive cytokines and chemokines, including CXCL12, CXCL10, CCR5, CCR10, CCL5, and CCR2, to exert their immunosuppressive effects." (PMID 37515314, 2023). "These ex vivo studies are consistent with our prior results where combined PD-1 and CCR2 blockade led to decreased numbers of exhausted CD4+ and CD8+ T cells and increased IFN-γ expression within the gliomas." (PMID 36685592, 2022). "Studies have demonstrated that GAMs were recruited to sites of gliomas via interaction between CCL2/MCP-1 which are basically generated by glioma cells as well as its receptor CCR2 which is secreted by GAM and by a CCL7/MCP-3-CCR1/CCR2/CCR3-crosstalk." (PMID 35419058, 2022). "Recombinant and glioma-derived CCL2 and CCL7 induce the migration of CCR2+/CX3CR1+ MDSCs with similar efficacy." (PMID 36685592, 2022). "Further studies will be necessary to better understand direct and indirect mechanisms whereby CCR2+/CX3CR1+ M-MDSCs disrupt T cell function and dampen immune responses in the context of glioma." (PMID 36685592, 2022). "CCL2 and CCL7 are produced, at least in part, by glioma cells and our study indicates that CCL2 and CCL7 function in a redundant manner to induce the migration of CCR2+/CX3CR1+ M-MDSCs into the glioma microenvironment." (PMID 36685592, 2022). "The released Kyn induced the expression of CCR2 by activating AHR, and advanced the recruitment of macrophages to tumor sites by enhancing the response to MCP-1 secreted by glioma cells." (PMID 34211978, 2021). "In a murine glioma model, one week after GL261 cells had been injected into mice, flow cytometric analysis of the tumour tissues showed that CCR2 was largely localized to MDSC populations." (PMID 34464477, 2021). "Under these conditions, not only the recruitment of TAMs is inhibited but also the attraction of regulatory T cells via CCR4 and the autocrine mechanism on glioma cells, expressing CCL2 and CCR2, is interrupted." (PMID 32668709, 2020). "We have been able to show variable CCR2 expression in human GBM tissues and high expression in murine gliomas." (PMID 32668709, 2020). "Targeting the ligand of CCR2, CCL2, in prostate cancer and glioma led to a reduction of tumor growth and prolonged survival." (PMID 32668709, 2020). "Upregulated IL-6 production in microglia stimulates glioma invasiveness, and it was suggested that the CCL2/CCR2/IL-6 loop represents a potential target to interfere with glioma invasion." (PMID 29258556, 2017). "CCR2+ cells were detected in all 17 glioma tissue samples, and CX3CR1+ cells were found in 12 of the 17 glioma tissue samples." (PMID 27602954, 2016).
glioma (continued). "Since CD3+ T-cells seem to respond to CCL2 in the inflamed parenchyma in the human glioma and monkey brain, we analyze their ability to express the CCL2 receptor (CCR2) in their cell surface." (PMID 22319587, 2012). "Preclinical models have shown that CCR2 antagonists such as CCX872 reduce the accumulation of immunosuppressive myeloid cells within tumors and enhance the efficacy of PD-1 checkpoint blockade, ultimately improving survival in glioma-bearing mice." (PMID 40867316, 2025). "Their findings revealed that the absence of CCR2 enhances the effectiveness of PD-1 blockade in KR158 glioma-bearing mice, leading to a previously unseen survival advantage." (PMID 40867316, 2025). "These bone marrow-derived CCR2+/CX3CR1+ cells also co-express markers that correspond to M-MDSCs, namely, CD45+, CD11b+, Ly6Chi, and Ly6G−, migrate to glioma-secreted CCL2 and CCL7, and suppress the proliferation and IFN-γ secretion of both CD4+ and CD8+ T cells." (PMID 39272914, 2024). "Additionally, monotherapy with CCX872, a CCR2 antagonist, improved median survival in an orthotopic model induced by KR158 glioma cells; these antitumor effects were further enhanced by the combination of CCX872 with anti-PD-1." (PMID 36980182, 2023). "Our earlier studies established that CCR2+/CX3CR1+ myeloid cells, characterized by M-MDSC markers (CD45, CD11b, Ly6Chi, and lack Ly6G), are present in the bone marrow and infiltrate into multiple murine gliomas (KR158B and 005 GSC)." (PMID 36685592, 2022). "Upon validating CCR2+/CX3CR1+ cell migration to the conditioned media of KR158B and KR158B CCL2 KD glioma cell lines, we sought to determine whether the migration was exclusively mediated by CCL2 and/or CCL7." (PMID 36685592, 2022). "To evaluate whether KR158B tumor cells are active contributors in the recruitment of CCR2+/CX3CR1+ cells, we tested whether glioma cells produced and secreted CCL2 and CCL7." (PMID 36685592, 2022). "We also saw no changes in the population of CCR2+/CX3CR1+ cells in the bone marrow of mice harboring chemokine knockdown gliomas." (PMID 36685592, 2022). "CCR2 inhibition was reported to reduce CD11b+/Ly6Chi/PD-L1+ MDSC enrichment in established gliomas and enhance PD-1 blockade efficacy in anti-PD-1 resistant gliomas." (PMID 35920986, 2022). "Also, a study revealed that IL-1β secreted by both microglia and macrophages stimulated the p38 mitogen-activated protein kinase (MAPK) pathway in glioma cells, which in turn results in augmented secretion of CCL2—the agonist for CCR2 on microglia." (PMID 35419058, 2022). "As a special member of glioma TME, microglia are recruited to lesions through CX3CL1/CX3CR1 chemokine channel, while peripheral monocyte-macrophages through the MCP-1/CCR2 channel." (PMID 34211978, 2021). "In contrast, macrophages in glioma TME with CX3CR1 expression were differentiated from CX3CR1lo peripheral monocytes entered the cranial cavity, which highly express CD45 and CCR2." (PMID 34211978, 2021). "The combination of PD-1 blockade and CCR2 inhibition (both genetic and pharmacological with the CCR2 agonist CCX872) improved survival of KR158 glioma-bearing mice, and reduced accumulation of CD11b+/Ly6Chi/PD-L1+ MDSCs in gliomas." (PMID 34504786, 2021). "It has been reported that microglia cells and macrophages in the glioma microenvironment could secrete chemokine CCL2 to recruit CCR4+ Treg and CCR2+ ly‐6C+ Monocytic MDSCs and suppress tumor immunity." (PMID 34482648, 2021). "By adoptively transferring classical or nonclassical monocytes from Cx3cr1GFP/+ mice into Ccr2-KO mice harboring orthotopically transplanted gliomas, the authors demonstrated that only classical monocytes were able to differentiate into MDMs within the tumor." (PMID 34539650, 2021). "In GSCs, celecoxib revealed significant decrease in mRNA levels of Ccl2 and Cxcr3 but not of Ccr2 and Cxcl10, which was consistent with the high mRNA levels of Ccl2 in the glioma model and GSCs but none of Cxcl10 in GSCs." (PMID 32943658, 2020).
glioma (continued). "In line with the current literature, we assume that the reduced accumulation of TAMs in glioma tissue of Ccr2KO mice is predominantly due to diminished CCR2-dependent migration rather than alteration of their cellular activity." (PMID 32668709, 2020). "It was shown that increased expression of CCR2, a receptor for CCL2, also stimulates the recruitment of TAMs and fibroblasts at the primary tumors, where they enhance invasion, angiogenesis, and metastasis of glioma and other cancers." (PMID 32456359, 2020). "Yet, the precise function of CCR2-signaling for glioma progression as well as angiogenesis has not been elucidated." (PMID 32668709, 2020). "Using the Ccr2-/- knockout model, severe glioma microenvironmental alterations were uncovered, which do not appear beneficial." (PMID 32668709, 2020). "Here, we studied the importance of paracrine signaling in the glioma microenvironment by focusing on the celecoxib-mediated role of chemokines C–C motif ligand 2 (CCL2), C-X-C ligand 10 (CXCL10), and their receptors, CCR2 and CXCR3, in GSCs and a GSC-bearing malignant glioma model." (PMID 32943658, 2020). "We assume that if the entire CCR2/CCL2 signaling axis is inflicted by antibody treatment, tumor growth is inhibited, while specific knockout of tumor microenvironmental cells by using a Ccr2-/- transgenic mice leads to enhanced glioma progression." (PMID 32668709, 2020). "A recent study described only a small impact on the survival of glioma-bearing Ccr2 transgenic mice whereby tumor volumes were not evaluated." (PMID 32668709, 2020). "We newly found that in the mouse glioma model, celecoxib decreased mRNA levels of Ccl2, CxcL10 and Cxcr3 but not of Ccr2 and protein expression of CCL2 and CXCL10 in the tumor and peri-tumor." (PMID 32943658, 2020). "As expected, Ccr2KO mice did not express Ccr2 following 21-days of glioma growth, in strong contrast with WT animals." (PMID 32668709, 2020). "Overexpression of CCR2, CCR4, CXCR1/2, and CXCR4 reportedly improved CAR T cell trafficking to brain tumors in preclinical studies.CAR T cell pretreatment with metformin/rapamycin also enhanced mitochondrial respiration, leading to improved CAR T cell efficacy in glioma." (PMID 40895575, 2025). "Similarly, expression of CCR2 and CCR4 on CAR T cells could increase chemotaxis to CCL2/4/5/17/22-secreting gliomas." (PMID 40895575, 2025). "In our study, we used Ccr2-/- mice in combination with the GL261 immunocompetent mouse glioma model to evaluate the importance of the CCR2 expression on the tumor microenvironment, especially on TAM recruitment and their phenotype as well as glioma vascularization." (PMID 32668709, 2020). "Furthermore, an astonishingly high proportion of primary human glial tumors overexpress CCR2 (whilst normal brain structures do not), suggesting possibly a similar mechanistic bonding to CCL2." (PMID 21943176, 2011). "Moreover, genetic and pharmacologic inhibition of CCR2 reduces the presence of these CD45+, CD11b+, Ly6Chi, Ly6G- cells in the TME, promotes sequestration of the cells in the bone marrow, and unmasks an effect of an immune checkpoint inhibitor to slow glioma progression." (PMID 36685592, 2022). "In conclusion, our findings suggest that downregulation of the CCL2/CCR2 and CXCL10/CXCR3 axes via inhibition of the NF-κB pathway in the tumor and the tumor microenvironment might have contributed to the antitumor effects of celecoxib observed in the mouse glioma model." (PMID 32943658, 2020). "However, celecoxib treatment did not alter CCR2 in the glioma model, we could not clarify the role of CCR2." (PMID 32943658, 2020). "CCR2 and CX3CR1 expressing cell populations were assessed via flow cytometry within the glioma microenvironment as well as non-tumor peripheral tissues: blood, spleen, and bone marrow." (PMID 36685592, 2022). "These CCR2+ MDSCs were recruited to the glioma microenvironment in response to CCL2, whereas MDSCs lacking CCR2 failed to maximally accumulate in the TME." (PMID 34464477, 2021).